MYCN (MYCN proto-oncogene, bHLH transcription factor)
Diseases named in the same sentence as MYCN in open-access papers (continued):
Sharing a sentence is not in itself a finding about the gene and the disease.
neuroblastoma (continued). "The treatment of a panel of MYCN-amplified as well as MYCN-single-copy neuroblastoma cell lines with HDAC8 inhibitors for 6 days significantly decreased cell numbers." (PMID 25695609, 2015). "Here we have shown that MYCN imparts neuroblastoma tumor-like characteristics, including enhanced proliferation, neural lineage commitment, and higher rates of cell death, to multipotent sympathoadrenal progenitor cells." (PMID 26222553, 2015). "In neuronal tumors such as neuroblastoma, MYCN is frequently activated by gene amplification, and reducing its expression by RNA interference has been shown to promote growth arrest and apoptosis of tumor cells." (PMID 25477524, 2015). "Eleven MYCN-targeting miRNAs have thus been identified, of which miR-34a, miR-101, let-7e and miR-202 were shown to affect neuroblastoma proliferation in vitro." (PMID 25294817, 2015). "Patients with MYCN-amplified neuroblastoma and segmental aberrations have a particularly poor prognosis, with an overall 5-year survival rate of only 30%1." (PMID 26399178, 2015). "MiR-9 is activated by MYC/MYCN-mediated E-cad downregulation resulting in metastases of neuroblastomas and breast tumors." (PMID 26110567, 2015). "Other classifications of neuroblastoma are based on the age, tumour differentiation histologic appearance and genetic factors including oncogene MYCN, aberrations in 11q and tumour cell ploidy." (PMID 26010602, 2015). "Several studies reported that with the down regulation of MYCN expression in neuroblastoma cells induced cell apoptosis, morphological differentiation and cell growth arrest at the G1phase." (PMID 26010602, 2015). "Understanding this regulatory miRNAome upstream of MYCN in neuroblastoma can open new perspectives for targeting the MYCN pathway in neuroblastoma tumors, a strategy that holds great promise." (PMID 25294817, 2015). "For instance genes that maintain the balance between proliferation and differentiation of neural crest cells, such as MYCN, ALK and PHOX2B, are often found mutated or overexpressed in high-risk neuroblastomas." (PMID 25797249, 2015). "Recently, inhibition of Brd proteins, most notably Brd4, has been shown to be effectively down-regulating MYCN functions at least in preclinical models of embryonal tumors including medulloblastoma and neuroblastoma." (PMID 26029996, 2015). "MLN8237 is effective in MYCN-driven transgenic mouse models of neuroblastoma (TH-MYCN), in which high-level expression of MYCN is driven in neural crest by a tyrosine hydroxylase (TH) promoter." (PMID 25785590, 2015). "Nevertheless, the spectrum of chromosomal aberrations in these MYCN-driven murine tumors recapitulates many of the observed chromosomal imbalances observed in human neuroblastomas." (PMID 25174395, 2015). "Selective sensitivity based on MYCN status was recently shown for the AURKA inhibitor MLN8237 in neuroblastoma which is due to the stabilizing effect of AURKA on MYCN." (PMID 26497213, 2015). "Accordingly, glutamine deprivation depletes TCA cycle intermediates and induces dramatic cell death in MYCN-amplified neuroblastoma cells." (PMID 26528759, 2015). "We present here for the first time the integrative profiling of thirteen MYCN-amplified neuroblastoma cell lines at the genomic, transcriptomic and translatomic levels." (PMID 26399178, 2015).
neuroblastoma (continued). "Given that sympathoadrenal progenitor cells (SAPs) are the likely cells of origin for neuroblastoma, and that MYCN plays a key role in neuroblastoma development and prognosis, it is important to understand the effects of MYCN expression on SAPs." (PMID 26222553, 2015). "Nevertheless, results shown here depicted a new layer of regulation in control of tumor glutamine metabolism and provided a molecular explanation for the functional significance of GLS2 overexpression observed in MYCN-amplified neuroblastomas." (PMID 26528759, 2015). "In a study of 116 neuroblastoma, p-Akt(Ser473) and p-Akt(Thr308) expression correlated with markers of poor prognosis, such as MYCN amplification, changes in 1p36, and stage IV disease." (PMID 26793165, 2015). "The relationship between SLC19A1 and MYCN expression was examined in tumors from two independent patient cohorts, in a panel of 13 neuroblastoma cell lines and in cell lines with inducible and silenced MYCN expression." (PMID 25860940, 2015). "Although MYCN has important prognostic value, amplification is only observed in about 25% of neuroblastoma cases and it remains largely to be defined what other factors contribute to high-risk neuroblastoma." (PMID 25266063, 2015). "A previous in vitro study has shown that the glycolytic inhibitor 2-deoxyglucose (2DG) induces glucose deprivation and suppresses tumor cell growth in neuroblastoma, especially in those types with MYCN amplification." (PMID 26398947, 2015). "Inhibition of MYCN expression in vitro results in maturation of neuroblastoma cell lines, with neurite outgrowth and upregulation of the differentiation markers neurofilament and GAP43." (PMID 26222553, 2015). "Data obtained from mRNA profiling of 101 primary neuroblastoma were re-analyzed for correlation of cell cycle genes with outcome and the MYCN amplification status." (PMID 26029996, 2015). "The oncogene MYCN was originally identified in neuroblastoma cells, and it has been reported as a prognostic marker in patients with neuroblastoma." (PMID 25351211, 2015). "Subsequent to these findings it was proposed that Aurora A is essential for the growth and survival of MYCN-amplified neuroblastoma cells." (PMID 26380220, 2015). "MYCN acts as a major driver oncogene in neuroblastoma, a pediatric tumor of the sympathetic nervous system." (PMID 25294817, 2015). "MYCN is a commonly amplified gene in neuroblastoma tumors, therefore we determined its copy number levels as well in the same panel of cell lines." (PMID 25658463, 2015). "Several studies have also demonstrated antitumor activity of Aurora A inhibition in MYCN-amplified neuroblastoma models." (PMID 26380220, 2015). "In order to assess the effects of pharmacologic inhibition of PI3K on MYCN-driven cells, human Kelly MYCN-amplified neuroblastoma cells were treated with various PI3K inhibitors: PI-103, LY-294002, PIK-75, and PW-12." (PMID 26029667, 2015). "Later, an additional mechanistic study shown that Aurora-A forms a complex with MYCN in MYCN-amplified neuroblastoma cells, which protects MYCN from proteasomal degradation in mitosis." (PMID 26734566, 2015). "Soon after its discovery, amplification of MYCN was found to correlate with poor prognosis in neuroblastoma patients, and amplification is routinely assayed in the clinical setting to stratify risk." (PMID 26222553, 2015). "It has also been shown that silencing MYCN in neuroblastoma cell lines results in apoptotic cell death." (PMID 26222553, 2015). "The majority of MYCN-targeting miRNAs in neuroblastoma showed a decrease in expression during murine MYCN-driven neuroblastoma tumor development." (PMID 25294817, 2015).
neuroblastoma (continued). "Altogether, these data suggest that N-Myc promotes oxidative glutamine metabolism predominantly through selective GLS2 induction in MYCN-amplified neuroblastoma cells." (PMID 26528759, 2015). "Amplification of MYCN is also detected in neoplasias of the central nervous system, although at lower frequency than neuroblastoma." (PMID 26029658, 2014). "The positive feedback regulation formed in the MYCN/NCYM-amplified tumors promotes the aggressive nature of human neuroblastoma." (PMID 24391509, 2014). "The expression of MMP-9 by stromal cells has previously been shown to regulate the vascular architecture in a murine orthotopic MYCN-amplified neuroblastoma xenograft model by promoting pericyte recruitment." (PMID 24667968, 2014). "Among the known regulators of MYCN, NCYM is the only gene that shows 100% co-amplification with MYCN in human primary neuroblastomas." (PMID 24391509, 2014). "AURKA is necessary for the growth of MYCN amplified neuroblastoma providing an essential function in stabilization of NMYC protein." (PMID 25277175, 2014). "We next examined the number of apoptotic cells in neuroblastomas from MYCN transgenic mice and MYCN/NCYM double transgenic mice by staining for cleaved caspase-3." (PMID 24391509, 2014). "We focused on NCYM as a candidate gene that promotes the aggressiveness of MYCN-amplified neuroblastomas." (PMID 24391509, 2014). "End of treatment imaging revealed a mass adjacent to the right kidney, a biopsy of which showed neuroblastoma with MYCN amplification (hundreds of copies of MYCN probe in double minute pattern)." (PMID 24810334, 2014). "We next assessed the effect of OSU-03012 and VX-680 on the stability of MYC and MYCN in the neuroblastoma cell lines." (PMID 25017515, 2014). "The cytotoxicity of sunitinib was assessed in three neuroblastoma cell lines with different MYCN status using MTT assays." (PMID 24759734, 2014). "In further literature, the MYCN gene was knocked down in neuroblastoma cells, with a subsequence upregulation of the miR-21, concluding an inversely proportional relationship." (PMID 25548681, 2014). "There are ultrastructural morphological differences in neuroblastoma, dependent upon MYCN amplification status." (PMID 24679140, 2014). "For the neuroblastoma data set, the baseline probability was set to the estimated selection probability of the MYCN amplification status covariate." (PMID 25295525, 2014). "There is a relationship between ultrastructural features in neuroblastoma and MYCN status, although with marked overlap between groups." (PMID 24679140, 2014). "MYCN oncogene amplification and consequent N-Myc mRNA and protein over-expression, are seen in a quarter of tumors and correlate with poorer prognosis in neuroblastoma patients." (PMID 24742640, 2014). "Although CDK2 inactivation has been reported to induce apoptosis in MYCN-amplified neuroblastoma cells, in this study, siRNA-mediated CDK2 depletion failed to induce apoptosis in breast cancer cells." (PMID 24444383, 2014). "MYCN, a member of the myc family of proto-oncoproteins, regulates the expression of genes involved in the cell cycle, DNA damage and apoptosis, and overexpression of MYCN results in neuroblastoma development." (PMID 25365944, 2014). "The NCYM gene was co-amplified with the MYCN gene in all the cell lines and primary neuroblastomas we examined." (PMID 24391509, 2014). "NCYM was expressed in both primary and metastatic human neuroblastomas, and was co-expressed with the MYCN protein in cells of human neuroblastomas and the neuronal cells of the human cerebrum." (PMID 24391509, 2014). "The four majorly discussed genetic changes in neuroblastoma are MYCN protooncogene amplification, DNA content, and the allelic deletions on chromosomes 1p and 11q or the gain of 17q." (PMID 25548681, 2014). "We established MYCN/NCYM double transgenic mice as a new animal model for studying neuroblastoma pathogenesis." (PMID 24391509, 2014).
neuroblastoma (continued). "In neuroblastoma cell lines with normal MYCN copy number the presence of ACD is significantly higher than in cell lines with MYCN amplification." (PMID 24965943, 2014). "Transgenic mice expressing human MYCN in sympathoadrenal tissues spontaneously develop neuroblastomas, suggesting that MYCN alone can initiate tumorigenesis and promote tumor growth." (PMID 24391509, 2014). "In comparing the radiology of the novel Th-ALKF1174L/Th-MYCN and the well-established Th-MYCN genetically-engineered murine models of neuroblastoma using MRI, we have identified a marked ALKF1174L-driven vascular phenotype." (PMID 24667968, 2014). "NCYM knockdown did not affect the survival of the MYCN-single neuroblastoma cell lines, but promoted massive apoptosis of the MYCN-amplified neuroblastoma cells." (PMID 24391509, 2014). "In this study, we tested the growth suppressive effect of S(+)-ibuprofen, which is also an NSAID, in neuroblastoma cells and investigated the effect of S(+)-ibuprofen on MYCN/MYC expression in these cells." (PMID 24173829, 2014). "Somatically acquired genomic alterations with MYCN amplification (MNA) are key features of neuroblastoma (NB), the most common extra-cranial malignant tumour of childhood." (PMID 25013904, 2014). "Although tumor formation was not accelerated in the MYCN/NCYM double transgenic mice, the incidence of neuroblastomas with distant metastases was significantly increased in the MYCN/NCYM double transgenic mice." (PMID 24391509, 2014). "We investigated the impact of 21 SNPs on overall survival, event-free survival, age at diagnosis, MYCN status, and stage of the disease in 500 neuroblastoma patients." (PMID 25502557, 2014). "Our group has already achieved interesting results by using PNA-mediated inhibition of MYCN in neuroblastoma cell lines while other studies supported the possible applications of anti-gene oligonucleotide strategies in hematologic malignancies." (PMID 24334727, 2014). "MYCN transgenic mice, which express human MYCN in sympathoadrenal tissues, spontaneously develop neuroblastomas." (PMID 24391509, 2014). "Amplification of MYCN oncogene is found in approximately 20 % of all neuroblastoma patients and correlates with advanced disease stages, rapid tumor progression, and poor prognosis, making this gene an obvious therapeutic target." (PMID 24515800, 2014). "In the absence of a Th-ALKwt GEM model, it is difficult to conclude if intrinsic susceptibility MRI would be solely able to identify ALKF1174L-mutated MYCN amplified neuroblastoma, or more generally ALK-driven MYCN amplified neuroblastoma." (PMID 24667968, 2014). "We have shown that the combination of crizotinib and an inhibitor of downstream signaling induces a favorable response in transgenic mice bearing ALKF1174L/MYCN-positive neuroblastoma." (PMID 25228590, 2014). "Recent reports have suggested that both mutant ALK and Lin28B promote the growth of neuroblastomas in transgenic mouse models by targeting MYCN for stabilization or overexpression." (PMID 24391509, 2014). "NCYM expression levels were significantly correlated with that of MYCN in primary neuroblastomas (n = 106, P = 4.69×10−16) and in the tumors with a single copy of MYCN (n = 86, P = 1.11×10−13)." (PMID 24391509, 2014). "Our previous work also revealed that MYCN-inhibition leads to mitochondrial dysfunction resulting in accumulation of lipid droplets in neuroblastoma cells." (PMID 24859015, 2014). "Methylation level in 9 MYCN amplified neuroblastoma specimens was significantly lower, compared with that in 11 specimens without MYCN amplification (p=0.005, Mann-Whitney U test)." (PMID 24626568, 2014).
neuroblastoma (continued). "Toyoshima and co-workers found that CK1ε expression is significantly correlated with MYCN amplification in neuroblastoma and poor prognosis." (PMID 24904820, 2014). "Collectively, our results suggest that OSU-03012 affects multiple cellular targets, including Aurora kinase A, to exhibit its growth suppressive and MYC and MYCN-destabilizing effects in neuroblastoma and other cancer cells." (PMID 25017515, 2014). "There were significantly fewer NSG and NT in the cell body of the non-MYCN amplified neuroblastomas, but with markedly overlapping distributions." (PMID 24679140, 2014). "The phosphorylation levels of S6K in neuroblastomas from the MYCN/NCYM double transgenic mice were correlated with the expression levels of MYCN and NCYM (M7-M11)." (PMID 24391509, 2014). "Amplification of the MYCN oncogene and consequent over-expression of the N-Myc oncoprotein occur in 20-30% of primary untreated neuroblastoma tissues, and are highly correlated with advanced disease stage as well as poor patient prognosis." (PMID 24952595, 2014). "Previously we have reported that MYCN directly targets its own expression in neuroblastoma cell lines." (PMID 24391509, 2014). "It has been reported that MYCN knockdown decreases cell proliferation and induces apoptosis and/or differentiation in MYCN-amplified neuroblastoma cells." (PMID 24391509, 2014). "Since sunitinib inhibited phosphorylation of Akt we evaluated the effect of sunitinib on MYCN expression in neuroblastoma." (PMID 24759734, 2014). "Chen and Stallings were able to indicate that miR-184 has a significant role in the apoptosis of neuroblastoma with suggestions that MYCN also mediates tumorigenic effect by regulating the miRNAs." (PMID 25548681, 2014). "We next raised an antibody against the putative human NCYM protein, and identified a 12 to 15 kDa protein in human neuroblastoma cells which mainly localized to nuclei in MYCN-amplified neuroblastoma cells." (PMID 24391509, 2014). "In this study, we continued our effort to identify small molecules that can destabilize or downregulate MYC and MYCN protein expression in neuroblastoma cells." (PMID 24173829, 2014). "In contrast, we have recently demonstrated anti-tumorigenic effects of 10058-F4 in two tumor models of MYCN-amplified neuroblastoma, suggesting that direct MYC inhibition using a small molecule is achievable in vivo." (PMID 24859015, 2014). "In this study, we found that NCYM maintains the survival of MYCN-amplified neuroblastoma cells, and that the apoptotic cell number, indicated by cleaved caspase-3, was downregulated in MYCN/NCYM transgenic mice." (PMID 24391509, 2014). "In primary human neuroblastomas, NCYM is 100% co-amplified and co-expressed with MYCN, and NCYM mRNA expression is associated with poor clinical outcome." (PMID 24391509, 2014). "Overexpressed NCYM stabilizes both MYCN and β-catenin, and enhances the generation of neuroblastomas with increased aggressive behavior such as distant metastasis and/or drug resistance, which are characteristics reminiscent of human neuroblastoma." (PMID 24391509, 2014). "A missense SNP in exon 10 of the CASP8 gene SNP D302H was associated with worse overall and event-free survival in patients with MYCN-amplified neuroblastoma tumors." (PMID 25502557, 2014). "Since MYCN amplification is a well known adverse prognostic marker in neuroblastomas, this provides further support that the ALK D5F3 antibody is likely the most suitable among the three for ascertaining ALK protein expression status as a prognostic biomarker." (PMID 25188507, 2014). "MYCN and MYC play a crucial role in determining the malignancy of unfavorable neuroblastomas, whereas high-level expression of favorable neuroblastoma genes is associated with a good disease outcome and confers growth suppression of neuroblastoma cells." (PMID 24173829, 2014).